HMGA2 (high mobility group AT-hook 2)
Description:
Functions as a transcriptional regulator. Functions in cell cycle regulation through CCNA2. Plays an important role in chromosome condensation during the meiotic G2/M transition of spermatocytes. Plays a role in postnatal myogenesis, is involved in satellite cell activation (By similarity). Positively regulates IGF2 expression through PLAG1 and in a PLAG1-independent manner.
Synonyms: HMGIC; BABL; LIPO; HMGI-C; SRS5; STQTL9
Tractability: PROTAC: ubiquitination databases record sites on it.
Gene: Protein-coding gene on chromosome 12 (65,824,460 to 65,966,291, forward strand). Ensembl gene ENSG00000149948.
Subcellular location: Nucleus
Subcellular location (Human Protein Atlas): Nucleoli; Nucleoli rim; Nucleoplasm
Pathways (Reactome):
Cellular responses to stimuli: Formation of Senescence-Associated Heterochromatin Foci (SAHF)
Gene Ontology:
Molecular function: 5'-deoxyribose-5-phosphate lyase activity; C2H2 zinc finger domain binding; cAMP response element binding; DNA binding, bending; DNA-(apurinic or apyrimidinic site) endonuclease activity; MH1 domain binding; MH2 domain binding; minor groove of adenine-thymine-rich DNA binding; nucleic acid binding; nucleosomal DNA binding; protein binding; RNA polymerase II-specific DNA-binding transcription factor binding; SMAD binding; transcription cis-regulatory region binding; transcription corepressor activity; transcription coregulator activity; DNA binding; enzyme binding
Biological process: base-excision repair; chondrocyte differentiation; chondrocyte proliferation; endodermal cell differentiation; epithelial to mesenchymal transition; fat cell differentiation; heterochromatin formation; host-mediated suppression of viral transcription; intracellular signal transduction; mesenchymal cell differentiation; mesodermal cell differentiation; mesodermal-endodermal cell signaling; negative regulation of apoptotic process; negative regulation of DNA binding; negative regulation of DNA-templated transcription; negative regulation of double-strand break repair via nonhomologous end joining; negative regulation of single stranded viral RNA replication via double stranded DNA intermediate; negative regulation of transcription by RNA polymerase II; oncogene-induced cell senescence; positive regulation of DNA-templated transcription; positive regulation of gene expression; positive regulation of protein serine/threonine kinase activity; positive regulation of stem cell proliferation; positive regulation of transcription by RNA polymerase II; regulation of cell cycle process; and 11 more
Cellular component: nucleolus; nucleoplasm; nucleus; protein-DNA complex; senescence-associated heterochromatin focus; SMAD protein complex; nuclear chromosome; chromatin
Genetic constraint (gnomAD): Loss-of-function variants: 4 observed, 4.98 expected, observed/expected ratio (o/e) 0.8, 90% interval 0.39 to 1.69. That is too few expected variants to judge how well the gene tolerates losing a copy. Missense variants: 80 observed, 75.85 expected, observed/expected ratio (o/e) 1.05, 90% interval 0.88 to 1.27. Synonymous variants: 46 observed, 31.51 expected, observed/expected ratio (o/e) 1.46, 90% interval 1.15 to 1.84.
Gene-disease validity (ClinGen):
ClinGen rates the evidence that HMGA2 causes each of these diseases.
Silver-Russell syndrome 5 (autosomal dominant): Definitive.
Homologues: Orthologues: dog HMGA2 (99% identical), mouse Hmga2 (95% identical), rat Hmga2 (93% identical), zebrafish hmga2 (77% identical), guinea pig HMGA2 (64% identical).
Diseases named in the same sentence as HMGA2 in open-access papers:
HMGA2 is named in the same sentence as 337 diseases in open-access papers, as found by Europe PMC text mining. Sharing a sentence is not in itself a finding about the gene and the disease. The quoted sentences say what the papers report.
breast cancer (152 papers, 2003 to 2026). A primary or metastatic malignant neoplasm involving the breast. "In this study, we aimed to investigate HMGA2 associated ceRNA HOTAIR pathway in breast cancer patients." (PMID 40686703, 2025). "HMGA2 overexpression is associated with breast cancer (BC) cell growth, proliferation, metastasis, and drug resistance." (PMID 38753081, 2024). "Heightened expression of HMGA2 and its various mutations have been seen in countless cancers, especially breast cancer." (PMID 36132137, 2022). "The LncRNA HOX transcript antisense RNA (HOTAIR) is upregulated in breast cancer cell lines and samples, which has been associated to the progression of breast cancer due to its action on the miR-20a-5p/HMGA2 axis." (PMID 34026654, 2021). "High levels of cytoplasmic HMGA2 were associated with a favorable overall survival of breast cancer patients." (PMID 34302528, 2021). "In particular, high levels of cytoplasmatic HMGA2 were associated with a favorable overall survival of breast cancer patients." (PMID 34302528, 2021). "In our study, we aimed to clarify the role of HMGA2 in metformin‐inhibited breast cancer and its underlying regulatory mechanism." (PMID 32031335, 2020). "There was only one study for each that evaluated the association between HMGA2 expression and OS in pancreatic ductal adenocarcinoma, ampullary adenocarcinoma, breast cancer, ccRCC, intrahepatic cholangiocarcinoma, and hepatocellular carcinoma." (PMID 29997523, 2018). "The let-7 family appears to regulate the expression of RAS and HMGA2 in breast cancer cells and is associated with several mechanisms of carcinogenesis, including EMT." (PMID 25277099, 2014). "The HMGA protein family includes HMGA1a and HMGA1c, which are encoded by the same gene, and the closely related HMGA2, which is known to be over-expressed in breast cancer." (PMID 23307470, 2013). "We first assessed the potential functional significance of the unstudied deletion polymorphism rs10573247 at the 3′UTR of HMGA2 on miRNA binding using bioinformatic tools, and subsequently, the association between this polymorphism and breast cancer susceptibility was investigated." (PMID 38802807, 2024). "Of note, overexpression of HMGA2 in breast cancer has a strong association with metastasis." (PMID 36132137, 2022). "Importantly, HMGA2 is implicated in regulating breast cancer cell growth, invasion and 5-FU resistance mediated via nuclear paraspeckle assembly transcript 1 (NEAT1)." (PMID 34281530, 2021). "HMGA2 overexpression has been reported to be associated with tumorigenesis and progression in many human cancers such as esophageal squamous cell cancer, lung cancer, pancreatic cancer, breast cancer and colorectal cancer." (PMID 29997523, 2018). "We also identified three SNPs at 2q35, the most significant of which had r2 = 0.48 with a variant associated with breast cancer, and SNP rs12424086 located close to the HMGA2 gene and 6 kb away from rs1042725, the SNP identified by a GWA study for adult and childhood height." (PMID 20195514, 2010). "Additionally, HMGA2 expression in patients with breast cancer has been shown to be associated with poor prognosis and metastasis." (PMID 17222355, 2007). "Also, HOTAIR Although HMGA2 is highly expressed in most malignant tumors, including ovarian and pancreatic cancer, there are limited studies on its association with tumor formation and progression in breast cancer." (PMID 40686703, 2025). "The overexpression of HMGA2 mRNA has been shown to be closely associated with high histologic grade in breast cancer, suggesting that the expression level of the HMGA2 protein/gene could be a potential clinicopathological marker with prognostic implications for a wide range of cancers." (PMID 14647145, 2003). "It has been reported that LINC01121 promoted the development of breast cancer cells through the miR-150-5p/HMGA2 axis." (PMID 41488287, 2026).
breast cancer (continued). "This study aims to investigate the HMGA2 associated HOTAIR pathway, which has been implicated in carcinogenesis in breast cancer patients, at the molecular level and to evaluate its clinical significance." (PMID 40686703, 2025). "Comparative analysis across breast cancer cell lines revealed significantly higher HMGA2 expression in TNBC cell lines than in MCF7 and T-47D cell lines." (PMID 40475780, 2025). "First, expressions of HOTAIR/miR20a-5p/HMGA2 genes were quantified and compared in breast cancer patients (n = 40) and healthy controls (n = 10)." (PMID 40686703, 2025). "The architectural transcription factor high mobility group AT-hook 2 (HMGA2) is highly overexpressed in various types of cancer (e.g., colorectal cancer, liver cancer, breast cancer, uterine leiomyomas) and significantly correlated with poor survival rates." (PMID 38361784, 2024). "For example, HOTAIR competitively binds to miR-20a-5p to block the latter’s interaction with high mobility group A2 (HMGA2) mRNA, thereby increasing the protein levels of HMGA2, and resulting in aggravation of tumorigenicity of breast cancer cells." (PMID 38366205, 2024). "This was also supported by a recent reference that HMGA2 is a key oncogene in breast cancer, indicating the reliability of our results." (PMID 38845972, 2024). "Consistent with previous studies, the HMGA2 oncogenic pathway is shown to be enhanced by STAT3 signaling modulated Let-7a expression in breast cancer and glioblastoma cells 39-41." (PMID 39664573, 2024). "The HMGA2 gene plays a role in carcinogenesis, and previous studies have shown that HMGA2 mRNA is overexpressed in breast cancer." (PMID 38802807, 2024). "lncRNA HOTAIR acts as a molecular sponge of miR‐20a‐5p and, as ceRNA, it affects the activity and regulates the miR‐20a‐5p target genes, like HMGA2, thus contributing to breast cancer (BC) development and tumorigenesis." (PMID 37143733, 2023). "HOTAIR affected and blocked the growth, metastasis, and apoptosis of breast cancer cells through the miR-20a-5p/HMGA2 axis." (PMID 37404755, 2023). "Zhao, W, Geng, D, Li, S, Chen, Z, Sun, M. LncRNA HOTAIR influences cell growth, migration, invasion, and apoptosis via the miR-20a-5p/HMGA2 axis in breast cancer." (PMID 38100296, 2023). "Let-7 negatively regulates Harvey-RAS (H-Ras) and high-mobility group AT-hook 2 (HMGA2), suppressing differentiation and self-renewal of breast cancer stem-like cells." (PMID 36674935, 2023). "For example, our previous IP studies had identified the early DNA damage sensor PARP1 as an interaction partner of HMGA2 in human breast cancer cells." (PMID 36835656, 2023). "We focused on XRCC6/Ku70 and demonstrated co-precipitation of Ku70 with HMGA2 from MDA231 human breast cancer cell nuclear extracts." (PMID 36835656, 2023). "LncRNA HOTAIR can serve as a molecular sponge for miR-20a-5p and markedly facilitates breast cancer malignant progression through activation of HMGA2 protein expression." (PMID 36787056, 2023). "We confirmed the interaction of HMGA2 with XRCC6/ Ku70 by co-IP in human MDA231 breast cancer cells." (PMID 36835656, 2023). "In another example, by serving as a competing endogenous RNA for miR-511-3p, LINC02163 upregulated the level of high mobility group A2 (HMGA2) and promoted the progression of breast cancer." (PMID 35392234, 2022). "miR-511-3p sponged by LINC02163 restrains the malignant properties of breast cancer by targeting HMGA2." (PMID 34989314, 2022). "The expression of MALAT1 is upregulated, and MALAT1 can promote the expression of high mobility group A2(HMGA2) by sponge miR-26b, thereby promoting the development of breast cancer." (PMID 35707365, 2022). "METTL3 targeted MALAT1/miR-26b/HMGA2 axis and caused EMT and promotion of migration and invasion in breast cancer." (PMID 36212476, 2022). "High-mobility group AT-hook 2 (HMGA2) functions as an oncogenic protein and has been implicated in the development of various cancers, including breast cancer." (PMID 36230935, 2022).
breast cancer (continued). "In breast cancer (BC) studies, circARL8B inhibited tumor lipid metabolism and cell proliferation through the miR-653-5P/HMGA2 axis." (PMID 36452489, 2022). "RKIP has been shown to suppress the expression of many prometastatic genes in TNBC cells by inhibiting HMGA2 expression in the mammary tumors." (PMID 33668453, 2021). "We can conclude that the m6A methyltransferase METTL3 controls epithelial-mesenchymal transition of breast cancer through the MALAT1/miR-26b/HMGA2 axis." (PMID 34419065, 2021). "To confirm the HMGA2 mRNA expression in different breast cancer subtypes, we used the tab OncoPrint to analyze the data based on an invasive breast cancer (TCGA, Nature 2012) dataset." (PMID 34680349, 2021). "HMGA2 3′-UTR is directly targeted by miR-142-3p, inducing a decrease in HMGA2 protein and suppressing breast cancer malignancy." (PMID 34439740, 2021). "The transcription factor high mobility group protein A2 (HMGA2) plays an important role in the pathogenesis of some cancers including breast cancer." (PMID 34356120, 2021). "In our recent study, we showed that miR-330 targets HMGA2 and stable induction of miR-330 expression inhibits Snail1 and increases E-cadherin expression in breast cancer cells." (PMID 33668453, 2021). "Our recent study demonstrated that HMGA2 suppression inhibits breast cancer EMT by affecting the TGF-β pathway and reducing the Smad3 transducer to further reduce Snail1 levels." (PMID 33668453, 2021). "In our recent studies of the role of HMGA2 in breast cancer, we demonstrated its overexpression in this cancer type and further showed that HMGA2 supports important oncogenic features in these cancer cells." (PMID 34680349, 2021). "For example, circHMCU modulates breast cancer cell proliferation and mesenchymal characteristics by sponging let-7 miRNAs and, subsequently, activates let-7 targeted genes, including HMGA2, c-myc and CCND1." (PMID 34572067, 2021). "The rescue experiments confirmed that HMGA2 overexpression reversed the suppressive influence of miR-216b on the 5-FU resistance of breast cancer." (PMID 34281530, 2021). "Of interest, the oncogene HMGA2 is also a master regulator of OSM-induced epithelial plasticity in breast cancer and can be induced by OSM, as we described in previous sections." (PMID 34361105, 2021). "To test HMGA2 effects on cell apoptosis, we performed annexin V-FITC/PI and DAPI stainings on HMGA2 silenced human breast cancer cells." (PMID 34356120, 2021). "In summary, we successfully prepared a novel type of cancer-targeting functionalized G4/MTX-siRNA nanocomplex for the efficient delivery of MTX and anti- HMGA2 siRNA to target and treat folate expressing human breast cancer (MCF-7 and MDA-MB-231) cells." (PMID 34356120, 2021). "It was reported that HMGA2 expression is upregulated in most malignancies, including lung, colorectal and breast cancer." (PMID 34680349, 2021). "Our cell cycle analysis revealed a significant arrest of G2/M in cells with stable HMGA2 knockdown, supporting our previous results showing that HMGA2 overexpression enhanced proliferation in breast cancer cells." (PMID 34680349, 2021). "It has been reported that HMGA2 acts as an oncogene and is overexerted by various cancers, including colon cancer, ovarian cancer, pancreatic cancer, and breast cancer." (PMID 34356120, 2021). "To investigate the gene promoter methylation status and expression level of HMGA2 in different breast cancer subtypes, we analyzed publicly available TCGA breast cancer datasets." (PMID 34680349, 2021). "Silencing HMGA2 expression using siRNA is expected to be an efficient approach to suppress breast cancer cell growth." (PMID 34356120, 2021). "Wnt10b/β-catenin signaling facilitates HMGA2 expression and cell proliferation in breast cancer, and miR-148a inhibits the invasion of colorectal cancer by targeting Wnt10b/β-catenin signaling." (PMID 34872582, 2021).
breast cancer (continued). "A luciferase reporter gene assay was performed to analyze the effect of metformin on HMGA2 promoter activity in breast cancer cells." (PMID 32031335, 2020). "In breast cancer cells, HMGA2 downregulation induced by miR-98 inhibited cell proliferation and caused apoptosis." (PMID 31963852, 2020). "In terms of function, treatment with metformin suppressed the proliferation of breast cancer cells and overexpressed HMGA2 reversed the inhibition of cell proliferation mediated by metformin." (PMID 32031335, 2020). "For the mechanism investigation, metformin inactivates oncogenic HMGA2 transcription through reducing transcription factor Sp1, leading to breast cancer growth inhibition." (PMID 32031335, 2020). "HMGA2 protein is overexpressed in many types of cancer including oral squamous cell carcinoma, lung cancer, breast cancer, gastric cancer, liver cancer, pancreatic cancer, colorectal cancer, ovarian cancer, and endometrial cancer." (PMID 32577156, 2020). "In mammary tumor cell lines stably expressing HMGA2 by vector transfection, primary tumors formed at a faster rate and exhibited higher metastatic potential to the liver parenchyma and lungs than tumor cells with empty vectors after inoculation in mice." (PMID 32365712, 2020). "We observed that the mRNA level of HMGA2 was markedly decreased by metformin in breast cancer cells." (PMID 32031335, 2020). "In breast cancer, retinoblastoma, and laryngeal squamous cell carcinoma, restoration of miR-98 with the consequent inhibition of HMGA2 expression reduced the proliferative and migratory abilities of cells, EMT, and metastasis formation in vivo." (PMID 31979076, 2020). "In this study, we were curious to ascertain the function of HMGA2 in metformin‐inhibited growth of breast cancer cells." (PMID 32031335, 2020). "HMGA2 mediates the proliferative response of tumor cells to WNT/-CATENIN signaling pathway in a Wnt10b-driven breast cancer model." (PMID 31963852, 2020). "Our data showed that the binding of Sp1 to HMGA2 promoter was abrogated by metformin in breast cancer cells." (PMID 32031335, 2020). "Metformin regulates transcription factor Sp1 to reduce HMGA2 activation, leading to the inhibition of breast cancer growth." (PMID 32031335, 2020). "The function of metformin‐regulated HMGA2 in breast cancer growth was tested using a cell viability assay." (PMID 32031335, 2020). "Based on the finding that metformin regulated HMGA2 in breast cancer cells, we finally analyzed the function of HMGA2 in metformin‐inhibited proliferation of breast cancer cells." (PMID 32031335, 2020). "Further, breast cancer progression is positively regulated by increased expression of high mobility group AT-hook 2 (HMGA2)." (PMID 31426393, 2019). "Chromatin remodeling factor, HMGA2 downregulation has been shown to stimulate TET1’s expression in breast cancer cells." (PMID 31426393, 2019). "Other studies have reported that high HMGA2 expression predicts poor outcome in breast cancer patients." (PMID 31484926, 2019). "In another study, miR-33b expression was shown to be inversely correlated with the presence of lymph node metastases in breast cancer patients and to inhibit stemness, migration and invasion potential in vitro by targeting HMGA2, SALL4 and Twist1." (PMID 31906022, 2019). "Subgroup analysis by cancer type revealed a significant correlation between HMGA2 expression and OS in gastric cancer, breast cancer, hepatocellular carcinoma, colorectal cancer, nasopharyngeal carcinoma, and esophageal carcinoma." (PMID 29416690, 2018). "HMGA2 inhibition after ectopic RKIP induction in breast cancer cell lines resulted in induction of miR200b, which in turn downregulated its direct target LOX, thus leading to decreased tumor cell invasion and metastasis." (PMID 30149591, 2018). "Yang and colleagues found that PAR1/HMGA2 pathway positively regulates invasion of breast cancer cell." (PMID 29659195, 2018).